MC1R (melanocortin 1 receptor)
Diseases named in the same sentence as MC1R in open-access papers (continued):
Sharing a sentence is not in itself a finding about the gene and the disease.
melanoma (continued). "Further work is required to pair this data with MC1R polymorphisms known to confer worse prognosis in melanoma and to assess the threshold below which MC1R-targeted therapies remains ineffective in melanoma tumors." (PMID 37790306, 2023). "A low frequency of high-penetrance gene variants and a high prevalence of MC1R variants found in our cohort emphasize the likely importance of MC1R variants in determining melanoma risk in our population." (PMID 37958811, 2023). "Here the authors show that depletion of the GPCR melanocortin-1 receptor (MC1R) in melanoma cells is associated with enhanced T cell infiltration and anti-tumor immune responses." (PMID 37714844, 2023). "Surprisingly, red-haired individuals (harboring MC1R polymorphism), which represent the skin phototype with the highest risk for melanoma development, have low nevus counts." (PMID 36834954, 2023). "A previous study showed that active MC1R and cAMP induction slowed the growth of melanoma cell lines by delaying G2/M progression caused by the increased inhibitory phosphorylation of cdc25B8." (PMID 37679505, 2023). "Melanoma risk determined by MC1R R variants varies from two to three times per R allele and is higher in the familial context when compared with the general population." (PMID 37958811, 2023). "It is described that patients with two MC1R variants have a higher melanoma risk compared to those with single variants." (PMID 37958811, 2023). "Although findings support association of genetic variants of MC1R of hair color and Parkinson’s disease (PD) risk it is still controversial that variants of MC1R account for co-occurrence of PD and malignant melanoma." (PMID 35452484, 2022). "The locus most highly associated with melanoma in our dataset was MC1R, which reflects previous reports." (PMID 35357426, 2022). "Only Gαs is expressed in melanocytes and melanoma and is activated by an associated receptor, such as the MC1R." (PMID 35158973, 2022). "In our patients, in two families both relatives harbored MC1R variants previously associated with increased melanoma risk (R and/or r alleles) and one family had one relative with two r alleles." (PMID 35085295, 2022). "Epidemiology studies have strongly established that the MC1R functions as a melanoma predisposition gene." (PMID 35158973, 2022). "The association between MC1R polymorphisms and melanoma risk is well established and is explained by defects in UV-induced tanning and protective eumelanin pigmentation." (PMID 36483028, 2022). "Genetic risk feedback based on the type of inherited melanocortin receptor (MC1R) variants carried in an individual is a promising approach to increasing melanoma risk awareness in those with a history of NMSC." (PMID 35959144, 2022). "Epidemiological evidence indicates that mutations in MC1R are genetic risk factors for melanoma in humans that are thought to act by loss of function." (PMID 35665216, 2022). "Melanocortin 1 receptor (MC1R) is a marker of the risk of melanoma overexpressed in more than 80% of melanomas." (PMID 35401191, 2022). "Correspondingly, loss-of-signaling MC1R polymorphisms are linked to an increased risk of melanoma and other skin cancers." (PMID 35740018, 2022). "It is plausible that as variants result in the loss of function of MC1R, this leads to a decline in eumelanin synthesis and, thus, leads to less effective protection against UV radiation and an increased risk of melanoma." (PMID 36551302, 2022). "Severe loss-of-function polymorphisms of MC1R contributes to red hair/fair skin and are associated with skin aging, and melanoma risk." (PMID 35197079, 2022). "The MC1R gene is known to be highly polymorphic in Caucasian populations, and those deficient in MC1R activity are characterized by red hair, fair skin, poor tanning, and an increased risk of melanoma and skin cancer." (PMID 36483028, 2022).
melanoma (continued). "Other melanoma-related genetic alterations consist of polymorphisms in genes coding for: melanocortin 1 receptor (MC1R) and melanocyte inducing transcription factor (MITF), also known as microphthalmia-associated transcription factor." (PMID 35158770, 2022). "MC1R is inactivated in people with red hair, due to polymorphism(s) that make(s) them more susceptible to melanoma than dark-skinned individuals." (PMID 35158973, 2022). "MC1R is associated with skin sensitivity to sunlight and is recognized as a tumor suppressor of melanoma." (PMID 36551302, 2022). "In three families, one or both relatives harbored MC1R variants previously associated with increased melanoma risk (low or high-risk variants)." (PMID 35085295, 2022). "Our analysis identifies established melanoma risk variants such as disruptive coding alleles of MC1R and TYR." (PMID 35357426, 2022). "Epidemiological studies suggest a link between the melanoma-related pigmentation gene melanocortin 1 receptor (MC1R) and risk of Parkinson’s disease (PD)." (PMID 35197079, 2022). "For example, the variant MC1R p.D294H7x49 (dbSNP id: rs1805009; superscript refers to GPCRdb generic residue numbers) is classified as a risk factor for melanoma and is reported to lose the capability to stimulate cAMP levels." (PMID 35639758, 2022). "Given the links among MC1R loss of function, red hair, melanoma, and PD, our findings also provide evidence of a possible MC1R basis for the well-established link between PD and melanoma." (PMID 35197079, 2022). "A meta-analysis on MC1R gene showed a significant association between Ile155Thr and the development of melanoma that were corroborated by the fact that this mutation impaired cAMP signaling." (PMID 35452484, 2022). "Identifying polymorphisms and mutations of the MC1R gene would enable a better understanding of melanoma susceptibility and potential treatments." (PMID 35465855, 2022). "The genes that carry a moderate melanoma risk include MC1R and MITF, whose protein products are involved in melanin synthesis." (PMID 35465855, 2022). "Aside from these phenotypic changes, recent studies also suggest that MC1R variants can independently elevate the risk of melanoma development." (PMID 34638397, 2021). "Nonetheless, the risk of developing melanoma appears to be higher as the number of MC1R variants increases in the carrier; it doubles in subjects with a single variant and can go as high as six times in a subject with two or more variants." (PMID 34442055, 2021). "The association of MC1R variants with BRAF kinase proto-oncogene somatic mutations has been investigated in melanoma, showing different results among several populations." (PMID 34356109, 2021). "MC1R polymorphisms in association with other susceptible genes for melanoma have also been reported." (PMID 34356109, 2021). "Carriers of at least one MC1R variant have a 5- to 15-fold increased risk confined only to BRAF+ melanomas, regardless the presence of chronic solar damage signs." (PMID 34356109, 2021). "A high number of acquired melanocytic nevi, the red hair phenotype and MC1R R alleles all independently increase melanoma risk." (PMID 34447610, 2021). "The loss-of-function MC1R variants (“R”) have been strongly associated with red hair color phenotype and increased melanoma risk." (PMID 34440462, 2021). "We found that among participants with MC1R variants associated with higher risk of melanoma, the intervention increased shade-seeking or using an umbrella, increased wearing sleeved shirts, and decreased sunburns among their young children." (PMID 34201795, 2021). "Among the common loci for melanoma susceptibility, the melanocortin 1 receptor MC1R is an outstanding gene." (PMID 34067022, 2021). "The aim of this review is to provide an update on the impact of MC1R gene in melanoma and NMSCs’ risk—together with the additional risk conferred by somatic mutation of other gene—as well as its role in the prevention of skin cancers." (PMID 34356109, 2021).
melanoma (continued). "Among those reporting a family history of melanoma, the precision prevention intervention improved hat-wearing and shade-seeking or umbrella use, findings similar to those observed among MC1R higher-risk participants." (PMID 34201795, 2021). "The nine most prevalent MC1R variants range in frequency from about 0.5 to 11% among these individuals, with each variant imparting a 1.5- to 2.7-fold increased odds of melanoma." (PMID 34201795, 2021). "Patients carrying the MC1R variants are presented with elevated melanoma risk, and MC1R had been a therapeutic target for melanoma." (PMID 34898475, 2021). "Polymorphisms of the melanocortin 1 receptor (MC1R) gene represent the most relevant gene for susceptibility to melanoma." (PMID 34571969, 2021). "Some single-nucleotide polymorphisms (SNPs) of MC1R are involved in the occurrence and development of melanoma." (PMID 34698109, 2021). "The relationship between the presence of MC1R variants and the age of melanoma diagnosis is controversial." (PMID 34442055, 2021). "Strikingly, considering the pigmentation-mediated effect of MC1R on melanoma risk prediction alone, it is smaller with any MC1R variant and each of the RHC and r variants." (PMID 34356109, 2021). "Darker-pigmented subjects present a significantly higher risk of melanoma associated with MC1R variants." (PMID 34356109, 2021). "The other cases of familial melanoma are likely due to inheritance of lower-penetrance predisposition genes such as MC1R (melanocortin 1 receptor) and MITF in combination with inheritance of polymorphisms." (PMID 34289891, 2021). "People with MC1R wildtype (WT) genotype and 20+ naevi have a similar melanoma odds ratio (OR) to people homozygous for the MC1R R allele (R/R) with 0–4 naevi (OR 4.82 vs. 4.42, respectively)." (PMID 33681261, 2021). "Pigmentation, UV responses, and melanoma risk are regulated by the MC1R gene (Wolf Horrell, Boulanger & D’Orazio, 2016)." (PMID 33986980, 2021). "The first is an isogenic system of MC1R loss-of-function in mouse melanocytes, while the second is an isogenic system of MC1R loss-of-function in the mouse B16 melanoma cell line." (PMID 33983985, 2021). "Inherited genetic variation at the melanocortin-1 receptor (MC1R) gene is a robust risk marker for melanoma among individuals of European ancestry." (PMID 34201795, 2021). "After removal of the MC1R region, the causal relationship between the genetic risk of melanoma in females (exposure) and endometriosis remained (b = 0.05, p = 0.03)." (PMID 36304021, 2021). "The inheritance of specific MC1R variants is a robust marker of increased risk of melanoma and keratinocyte skin cancers." (PMID 34439206, 2021). "Previous research has also suggested an association between both red hair and melanoma—for which MC1R variants are a risk factor—and PD30,31, and the MC1R protein was found to be neuroprotective in dopaminergic neurons, which are integral to PD pathology." (PMID 34584092, 2021). "Individuals carrying just one MC1R variant have almost 40% increased risk of melanoma, whereas carriers of two or more MC1R variants have more than a double risk, as compared to WT subjects." (PMID 34356109, 2021). "MC1R ‘R’ and ‘r’ variants, associated with red hair and fair skin sensitive to ultra-violet radiation and/or to melanoma development, were detected here at frequencies similar to previous reports." (PMID 34573422, 2021). "A later study confirmed that four frequent MC1R variants (Val60Leu, Val92Met, Arg151Cys, Arg160Tro) were associated with an increased melanoma risk in CDKN2A mutation carriers." (PMID 33076392, 2020). "The melanocortin one receptor (MC1R) is a melanocytic Gs protein-coupled receptor that regulates skin pigmentation, UV responses, and melanoma risk." (PMID 32973871, 2020).
melanoma (continued). "The associations between red hair color, redhead-related MC1R variants, and risk for both melanoma and PD support a possible role of systemic pigmentation in the PD-melanoma link." (PMID 32210791, 2020). "Loss-of-function MC1R variants are associated with red hair, fair skin, poor tanning and increased risk of melanoma." (PMID 32210791, 2020). "A direct comparison of MC1R polymorphism, sulfur and pheomelanin content, and melanoma markers among normal melanocytes, dysplastic nevi, and melanoma cells is envisioned to highlight the role of such a switch in the initiation of melanoma." (PMID 32850409, 2020). "MC1R RHC variants have also been associated with the likelihood of developing amelanotic/hypomelanotic melanomas." (PMID 32054529, 2020). "This study is the first to report the role of germline MC1R variants in influencing the somatic mutational landscape of melanoma from human data." (PMID 32714859, 2020). "The frequency of MC1R variant carriers in the general population is approximately 67% and seems also to be the case in melanoma patients." (PMID 32605315, 2020). "It is also known that the germline variants of MC1R that inactivate or reduce the function of the receptor have been linked to an increased risk of developing melanoma, especially under UV exposure." (PMID 32605315, 2020). "Individuals carrying MC1R variants are associated with a higher risk of melanoma, and MC1R had been used as an intervention target for melanoma." (PMID 32375704, 2020). "The correlation between MC1R variants and melanoma risk has been widely described in different populations." (PMID 33748184, 2020). "In an early study on Dutch melanoma families, the melanocortin-1 receptor (MC1R) variant Arg151Cys increased the risk of melanoma in carriers of a p16INK4a-inactivating deletion (known as p16-Leiden)." (PMID 33076392, 2020). "MC1R expression is associated with a higher risk of melanoma, and has been used as a target in melanoma therapy." (PMID 33680920, 2020). "Carriers of any MC1R variant have been shown to have a 66% higher risk of developing melanomas compared to wild-type (WT) subjects." (PMID 32605315, 2020). "Melanomas associated with germline mutations of MC1R have also been shown to have a significantly higher somatic mutational burden, suggesting a higher susceptibility to tumorigenesis in these patients." (PMID 32429485, 2020). "The α-MSH receptor, MC1R, is expressed in skin cells like melanocytes, and variants in MC1R are known risk factors for melanoma." (PMID 33301440, 2020). "In families of patients with melanoma, a more frequent occurrence of PD was observed; in patients with red hair color and MC1R polymorphism p.R151C, there was a more frequent occurrence of melanoma and PD." (PMID 33066407, 2020). "MC1R variants have furthermore been shown to increase the melanoma risk in families possessing cyclin-dependent kinase inhibitor 2A (CDKN2A) mutations." (PMID 32605315, 2020). "The identification here of ZDHHC13 as a critical regulator of MC1R function in vivo offers an alternative and potentially viable approach toward melanoma prevention in highly susceptible individuals." (PMID 30787281, 2019). "Many mutants of the MC1R gene (~200 mutants in the coding region) and the results from MC1R-knockout mice suggest that MC1R is a melanoma susceptibility gene." (PMID 31611597, 2019). "While many independent studies have demonstrated that melanoma risk is higher in people who carry MC1R RHC variants, the underlying mechanisms are only just being elucidated." (PMID 30787281, 2019). "Here we report that ZDHHC13 expression correlates with MC1R signaling and survival in human melanoma and that its expression can rescue MC1R RHC variant signaling in vitro and in vivo to suppress UVR-induced melanomagenesis." (PMID 30787281, 2019).
melanoma (continued). "Some MC1R variants are associated with red hair colour and fair phenotype, but they have been found associated with melanoma also in South European individuals with dark/olive phenotype." (PMID 31382929, 2019). "For the black coat color, a variant allele of the MC1R gene was found (marked as MC1R*2) to be associated with melanoma development." (PMID 31717496, 2019). "Collectively, these observations raise a key question: can therapeutic intervention directed toward enhancing MC1R signaling reverse the increased melanoma risk associated with MC1R RHC variants?" (PMID 30787281, 2019). "Melanocortin 1 receptor (MC1R) gene variants are associated with red hair and fair skin, a skin phototype with higher risk of melanoma development." (PMID 31717496, 2019). "Some genetic melanocortin-1 receptor (MC1R) variants responsible for human red hair color (RHC-variants) are consequently associated with increased melanoma risk." (PMID 30787281, 2019). "Although direct comparisons are difficult, the magnitude of the correlation with somatic SNV burden appears to be similar between BRN2 and that recently reported for melanocortin 1 receptor red hair color variants that are important risk factors for melanoma." (PMID 30804224, 2019). "Melanocortin-1 receptor is a palmitoylated protein and variants of the receptor are associated with red hair colour and susceptibility to melanoma." (PMID 30787281, 2019). "In most cases the association was with MC1R variants, which in turn, have been demonstrated to be associated to a higher risk of melanoma in numerous studies." (PMID 31382929, 2019). "In Caucasians with melanoma, MC1R variants were detected in 15–33% of dark-haired subjects and 42% of dark-eyed subjects; MC1R variants possibly negate the protective effects of dark pigment." (PMID 30787281, 2019). "Human studies and mouse models have demonstrated that MC1R genetic variants are tightly correlated with phenotypes, such as red hair, fair skin, freckling, UV irradiation sensitivity, and melanoma risk." (PMID 30787281, 2019). "Low frequency variants conferring moderate risk of melanoma were identified in two genes, MC1R and MITF, which play a key role in melanocyte biology and pigment synthesis regulation." (PMID 29963229, 2018). "Twenty-four percent of melanoma patients carry MC1R loss-of-function variants, and although redheads who express two MC1R loss-of-function alleles comprise only 1–2% of the worldwide population, they represent 16% of all melanoma patients." (PMID 30205559, 2018). "Forty-two out of 52 familial melanoma patients had been genotyped for 6 polymorphisms of MC1R (rs11547464, rs1805007, rs1805009, rs1805006, rs1805005, and rs2228479) in a previous study by our team." (PMID 29774366, 2018). "The aims of this study were to report the incidence of CDKN2A and CDK4 variants in a series of Greek familial melanoma families and to examine their association with epidemiological and clinical factors, as well as MC1R polymorphisms." (PMID 29774366, 2018). "A cross-sectional study was conducted by genotyping CDKN2A/CDK4 variants and selected MC1R polymorphisms in 52 melanoma-prone families." (PMID 29774366, 2018). "25–50% of familial MM relatives display a mutation in CDKN2A and variants in MC1R are common in the white population, conferring low to moderate risk to develop melanoma." (PMID 29998107, 2018). "Associations between genetic variation in MC1R and malignant melanoma, vitiligo (a disease characterized by depigmented skin and hair resulting from autoimmune destruction of epidermal melanocytes) and pigmentation traits have been reported." (PMID 29771307, 2018). "These patients also display a higher risk of melanoma, initially related only to the role of MC1R in pigmentation." (PMID 29081790, 2017).